CTLA4 (cytotoxic T-lymphocyte associated protein 4)
Diseases named in the same sentence as CTLA4 in open-access papers (continued):
Sharing a sentence is not in itself a finding about the gene and the disease.
melanoma (continued). "As for CTLA-4, Ipilimumab, a drug approved by FDA, docked to the MYPPPY motif of CTLA-4 and showed efficacy in inhibiting CTLA-4 in RCC, prostate cancer, cervical cancer, CRC, NSCLC, gastric cancer, pancreatic cancer, ovarian cancer, urothelial cancer, and melanoma." (PMID 34088360, 2021). "Preliminary results of a clinical study report that the combination of the anti-CTLA-4 antibody ipilimumab and anti-PD1 antibody nivolumab elevated the objective response rate (ORR) and the progression-free survival of patients with BRAFWT metastatic or unresectable melanoma." (PMID 34526987, 2021). "Although the exact mechanisms of action of CTLA-4 blockade remain unclear, the addition of anti-CTLA-4 to anti-PD-1 antibody demonstrated superior anti-tumor effects in various malignancies, including melanoma, kidney, and lung cancer." (PMID 34638390, 2021). "However, B16 melanoma failed to respond to anti-CTLA4 therapy due to a lack of CTLA4 expression on target cells and a reduced number of FcγR expressing effector cells." (PMID 33391547, 2021). "However, the existing evidence did not suggest that the neoadjuvant PD‐L1 plus CTLA‐4 inhibitors therapy shows better clinical outcome than PD‐L1 treatment in melanoma, oropharynx cancer, and oral cavity squamous cell carcinoma." (PMID 34766136, 2021). "We have recently demonstrated that in advanced melanoma, patients with low expression of MHC-I on the surface of tumor cells, were unlikely to benefit from anti-PD-1 monotherapy but could still respond to the combined treatment (anti-PD-1 and anti-CTLA-4)." (PMID 34201655, 2021). "To test the utility of CTLA4 methylation as a predictive biomarker for response to anti-CTLA-4 immune checkpoint blockade in stage IV melanoma patients, we identified retrospectively 30 patients diagnosed with advanced melanoma and treated with anti-CTLA-4 antibody ipilimumab monotherapy." (PMID 33196890, 2021). "However, it must be noted that anti-CTLA-4 monotherapy alone plays almost no role in melanoma therapy any longer." (PMID 34621681, 2021). "As for the treatments of melanoma, over the past decades, the management of melanoma has rapidly developed with the introduction of novel drug classes, such as BRAF and MEK pathway-targeted inhibitors and targeting immune check-point inhibitors consisting of CTLA-4, PD-1, PD-L1, and PD-L2." (PMID 33688507, 2021). "The advent of immune checkpoint inhibitors (e.g., anti-PD-L1, anti-PD-1, anti-CTLA4) and the targeted inhibition of the MAPK pathway with BRAF and MEK inhibitors in BRAF-V600-mutant melanoma patients has led to profound and durable tumor responses in some patients with advanced melanoma." (PMID 34065877, 2021). "In parallel to targeted therapies, immune checkpoint inhibitors (ICIs), anti-CTLA4 antibodies (ipilimumab) and anti-PD1/PDL1 antibodies (pembrolizumab, nivolumab, atezolizumab) have been successfully developed showing tumor regression and long-term durable disease control in melanoma patients." (PMID 34638331, 2021). "Melanoma treatment included surgery (90.9%, n = 10), radiation (9.1%, n = 1), and systemic therapy (e.g., cytotoxic chemotherapy, cytokine-based immunotherapy, or targeted) (81.8%, n = 9), with 54.5% (n = 6) receiving immune checkpoint inhibitors (ICI) (e.g., PD-1 and/or CTLA-4 inhibitor)." (PMID 34262818, 2021). "Furthermore, treatment with TA99 alone and in combination with anti-CTLA4, but not anti-CTLA4 alone, induced an increase in the percent of dendritic cells (CD11b+CD11c+) infiltrating B16 subcutaneous melanomas." (PMID 33520112, 2021). "However, anti-PDL1 and anti-CTLA4 treatments have additive and synergistic effects on cancer treatment, based on the observation of the superior efficacy obtained by using the combination of CTLA4 blockade and PDL1 blockade in patients with melanoma compared with monotherapy." (PMID 35127742, 2021).
melanoma (continued). "Notably, the authors did not include in their final meta-analysis anti-PD-L1 treatments because of lacking data, while the only two trials with anti-CTLA4 therapies are not commented in this article as they had only enrolled patients with melanoma.." (PMID 34769372, 2021). "Differences may exist between TRM populations, given that TRM extracted from NSCLC and melanoma do not express CTLA-4 and TRM originating from ovarian cancer only weakly express CTLA-4, TIM-3 and LAG-3." (PMID 34571883, 2021). "Ipilimumab against cytotoxic T-lymphocyte antigen 4 (CTLA4), nivolumab and pembrolizumab against programmed death 1 (PD1) as well as atezolizumab against programmed death-ligand 1 (PD-L1) are approved by the FDA for the treatment for advanced melanoma either as monotherapy or combination therapy." (PMID 34350118, 2021). "Combining CD73 inhibitors with both anti-CTLA-4 and anti-PD1 antibodies significantly increased the effect of immunotherapy through an increased frequency of tumor-infiltrating CD8+ T cells, suppressed Treg accumulation within tumor tissues in murine melanoma models, and enhanced T cell responses." (PMID 34073463, 2021). "It is interesting to note that in this model of B16 melanoma, isoform-specific inhibition with anti-TGFβ1 therapy and anti-PD-1 is superior to anti-PD-1 alone; however, TGFβ inhibition in combination with anti-CTLA-4 therapy did not produce synergistic effects." (PMID 34789823, 2021). "Similarly, no improved efficacy of anti-CTLA4 by AZD1152 was observed in BP or D4M-UV2 melanoma models." (PMID 33123754, 2021). "The presence of CTLA4+ Tregs in tumors and CTLA4– Tregs in adjacent tissues is in line with observations that anti‐CTLA4 therapies may target FOXP3+ Tregs to induce tumor rejection in melanoma." (PMID 34185431, 2021). "Then, we performed a pooled analysis on four melanoma cohorts treated with ICIs (the Robert cohort treated with anti-PD-1/L1 or anti-CTLA-4 or combination therapy, the Allen and Snyder cohorts treated with anti-CTLA-4 therapy, and the David cohort treated with anti-PD-1 therapy, n = 464)." (PMID 32903763, 2020). "Among the four bulk RNA-seq datasets, only the PRJEB23709 dataset had pre-ICT biopsies for melanoma patients treated with either anti-PD-1 (41 patients: 19 non-responders vs 22 responders) or the combination of anti-PD-1 and anti-CTLA-4 drugs (32 patients: 8 non-responders vs 24 responders)." (PMID 33033253, 2020). "In multiple murine tumor models, including the MC-38 and CT-26 colon tumors, the B16F10 melanoma and the RENCA renal cell cancer model, CPI-444 induced antitumor immune responses, and suppressed tumor growth as a single agent; it also augmented the efficacy of anti-PD-1/PD-L1 and anti-CTLA-4 agents." (PMID 32911819, 2020). "Similarly, mice engrafted with B16 melanoma in the brain 24 hours prior to ISV + α-CTLA-4 treatment demonstrated no improvement in survival (p=0.34, n≥13), compared with mice treated with α-CTLA-4 only." (PMID 32690669, 2020). "Although the preliminary trials on PD‐1, PD‐L1, and CTLA‐4 immunotherapy displayed encouraging outcomes with SCLC patients, it seems that the clinical efficacy of immunotherapy for SCLC was far less pronounced than that for solid tumors, such as NSCLC and melanoma." (PMID 32281704, 2020). "Unlike melanoma, anti-CTLA-4 monotherapy has not undergone extensive testing in the context of large phase III studies leaving open questions around its efficacy across diverse etiologies of chronic liver disease and its ability to induce long-lasting anti-tumour control." (PMID 32157213, 2020). "Thus, CTLA-4 blockade resulted in a significant increase of CD8+ T cells regardless of clinical responses in melanoma patients." (PMID 32194568, 2020). "Moreover, a phase I trial is investigating the combination of a peptide vaccine that targets IDO with anti-CTLA-4 inhibitors in patients with non-resectable melanoma." (PMID 32867025, 2020).
melanoma (continued). "Using single-cell suspensions prepared from malignant melanoma resections banked at MSK and classified as low or high based on their intracellular expression of IDO, we detected higher levels of immune-regulatory factors (IL-10, PD-L1, and CTLA-4) in IDOhigh samples compared to IDOlow samples." (PMID 32782249, 2020). "The group treated with anti-CTLA-4 showed the most improved outcomes among the single therapy groups which was expected since both MPLA and IDO inhibitors are used as treatment adjuvants as opposed to anti-CTLA-4, which is approved for treatment of a subset of melanoma patients as a single therapy." (PMID 32596146, 2020). "Furthermore, melanoma patients who did not respond to anti-CTLA-4 (ipilimumab) combined with stereotactic body radiotherapy showed an increase in the Kyn/Trp ratio during treatment compared to baseline Kyn/Trp." (PMID 33072086, 2020). "In the first two cohorts, a total of 110 patients with melanoma from the Allen cohort who received anti‐CTLA4 therapy and 75 patients with non‐small‐cell lung cancer (NSCLC) from the Hellmann cohort who received combined anti‐PD‐1 and anti‐CTLA4 therapy were analyzed." (PMID 32502294, 2020). "The expression of PD-1 and CTLA-4 on melanoma cells is not well studied." (PMID 32429485, 2020). "Thus, efforts to block CTLA-4 resulted in the advent of the monoclonal anti-CTLA-4 antibody, Ipilimumab, which was approved to be used as a checkpoint inhibitor for the treatment of melanoma." (PMID 32850353, 2020). "Equally, injection of aAPC particles loaded with both IL-2 and anti-CTLA-4 outperformed conventional single-release aAPCs, efficiently promoted sustained ICI and IL-2 release as well as antigen-specific T cell activation and expansion, and inhibited tumor growth in a murine melanoma model." (PMID 32942725, 2020). "Since 2011, much excitement has been generated in the melanoma field, with the development and US Food and Drug Administration approval of novel targeted therapies (e. g., small molecule BRAF and MEK inhibitors) and immune checkpoint inhibitor therapies (e. g., Anti-CTLA4 and Anti-PDL-1 antibodies)." (PMID 33378390, 2020). "To prove this, we treated mice with B16 melanoma with anti–CTLA-4 antibody, with and without Tα1." (PMID 32817121, 2020). "Moreover, at day 14 after melanoma cell transplantation, tumours from vaccinated mice showed increased absolute numbers of CD8+ TIL expressing PD-1, Nrp-1 and Tim-3 and, to a lesser extent, CTLA-4 and LAG-3." (PMID 31350404, 2019). "Moreover, whereas BayK8644 reinforced the antitumor effects of anti-PD-1 treatment in mouse melanoma, it did not enhance tumor growth inhibition induced by anti-CTLA-4 and anti-PD-1 combination therapy, at least in this model." (PMID 31085177, 2019). "Published studies explored the combination of single or dual CTLA4/PD-1 blockade together with DNA vaccines targeting the MYB oncoprotein for colorectal cancer, SSX2 cancer antigen for sarcoma, PSMA prostate-specific antigen, P815 mastocytoma and TRP-2 and gp100 melanoma-specific antigens." (PMID 31150505, 2019). "In melanoma, tumor PD-L1 expression showed a significant correlation with response to five out of eight iCPI studies treating patients with anti-PD-1 mAb, while it did not predict response to anti-CTLA-4 therapy." (PMID 31555274, 2019). "We have further demonstrated that the inhibition of TGF-β enhances anti-CTLA-4 antibody treatment in an autochthonous melanoma model, and that delayed inhibition of TGF-β, but not initial combinatorial therapy, improves anti-PD-1 antibody responses by reversing adaptive resistance." (PMID 31921140, 2019). "The importance of the immune system for tumor control seen in the Rnf5−/− mice was confirmed upon administration of antibodies depleting CD4+ or CD8+ T cells, which abrogated the ability of Rnf5−/− mice to inhibit melanoma tumor growth, with a small additive effect upon CTLA4, but not PD-1 blockade." (PMID 30940817, 2019).
melanoma (continued). "However, PD-L1, PD-L2 and CTLA-4 did not demonstrate higher expression in anti-PD-1-responsive melanoma patients." (PMID 29970158, 2018). "With regards to anti-CTLA-4-mAbs, it is interesting that selective blockade of sCTLA-4 can not only enhance antigen-specific CD4+ and CD8+ T-cell responses but also exert functional antitumor activity without requiring an interaction with full length CTLA-4 in a murine model of melanoma." (PMID 30482248, 2018). "Earlier attempts at releasing the suppression of conventional CD4+ and CD8+ T cells in CRC with anti-PD-1 and anti-CTLA-4 blockade, which have shown excellent results in therapy of advanced melanoma and prostate cancer, have failed, and so far no specific immunotherapy has been registered for CRC." (PMID 30651930, 2018). "Both CTLA-4 and PD-1 checkpoint inhibitors have resulted in increased patient survival in a number of studies, including studies on melanoma, renal cell carcinoma, squamous cell carcinoma, and non-small cell lung cancer, when compared to conventional chemotherapies." (PMID 29644214, 2018). "Mice with melanoma rich in macrophages had dramatically enhanced response to immune checkpoint inhibitors and survival when co-treated with IPI-549: Monotherapy with anti-CTLA-4 or anti-PD-1 produced total remission in 20% of cases whilst addition of IPI-549 increased this to 80%." (PMID 30191140, 2018). "We could speculate that melanoma cells are by themselves able to elicit a strong antitumor immune response potentially able to destroy the tumor if the immunosuppressive effect of CTLA-4 expression on T cell does not occur." (PMID 30545122, 2018). "Interestingly, a triple combination of anti-CTLA-4 + anti-PD-1 + radiotherapy induced complete responses in mouse pancreatic cancer and melanoma models, not seen with dual-checkpoint blockade alone." (PMID 30191140, 2018). "Previous reports from melanoma, NSCLC, and mismatch-repair deficient carcinomas also indicate that some tumors harboring extremely elevated mutational load do not derive clear benefit from PD-1 and CTLA-4 blockade." (PMID 30097571, 2018). "However, even the sole administration of ICIs results in severe colitis in fewer than <1% of patients, as shown in checkmate 037 and checkmate 066 (both melanoma trials using nivolumab) and checkmate 017 in SQ-NSCLC (nivolumab) and mentioned in treatment with anti-CTLA-4 antibody." (PMID 29983828, 2018). "Additionally, intratumoral and peripheral CD4+FOXP3−PD-1hi nonconventional Tregs in NSCLC as well as melanoma patients were reported as prognostic biomarkers for anti-PD-1 and anti-CTLA-4 therapies." (PMID 30546008, 2018). "Additionally, the loss of IFN-γ pathway genes IFNGR1, IFNGR2, JAK2, IRF1, IFIT1, IFIT3, MTAP, miR31 and amplification of the suppressor genes SOCS1 and PIS4 have been shown in melanoma patients non-responsive to anti-CTLA4 therapy." (PMID 30186768, 2018). "Indeed, ACT plus anti-PD-1, anti-PD-L1, or anti-CTLA4 synergistically reduced tumor growth in the MC38 carcinoma, B16 and B16F10 melanoma mouse models and increased the long-term survival in transgenic Her-2 mice upon ACT of Her-2+-specific CAR T cells and anti-PD-1 compared to the monotherapies." (PMID 27847783, 2016). "Nevertheless, anti-CTLA-4 treatment is generally not effective in non-melanoma tumors, which might for instance be due to a low fraction of tumor-reactive T cells in these tumors, high expression of PD-L1, or the secretion of anti-inflammatory cytokines." (PMID 27847783, 2016). "Finally, CTLA4 and TIM3 expression fall in distinct groups relative to CD8 T-cell infiltration in melanoma and kidney cancer, respectively, which might contribute to the varied clinical response to checkpoint blockade therapies." (PMID 27549193, 2016).
melanoma (continued). "A condition mimicking uveitis, an autoimmune reaction in the retinal pigment epithelium and the choroid of the eye, was reported in some melanoma patients undergoing immunotherapy with tumor-infiltrating lymphocytes plus IL-2, anti-CTLA-4 antibodies plus IL-2 with or without a gp100 vaccine." (PMID 27071457, 2016). "Currently, a phase I/II trial combining anti-CTLA-4 and anti-PD-1 therapy is ongoing in patients with solid tumors or sarcomas (NCT02304458), which will provide information about the efficacy and safety of double immune-checkpoint blockade in tumor types other than melanoma." (PMID 27847783, 2016). "Indeed, combination of drugs targeting CTLA-4 or the PD-1/PD-L1 pathway led to synergistic efficacy versus monotherapy in both murine models and patients leading to FDA approval of combination Ipilimumab and Nivolumab for advanced melanoma." (PMID 28031817, 2016). "The attractiveness of CTLA-4 as a target has been fueled by the development of two fully human monoclonal antibodies, tremelimumab and ipilimumab, which have gained FDA approval and have been incorporated into clinical guidelines for the treatment of advanced melanoma." (PMID 28536390, 2016). "In clinical trial, although only a subset of melanoma patients treated with anti-CTLA-4 antibody derived benefits, immunity-related adverse events of different severities occurred in approximately 64.2 % of melanoma patients treated with anti-CTLA-4 antibody, some of which were lethal." (PMID 25893809, 2015). "CTLA-4 inhibitors are currently available in the clinic; ipilimumab (BMS) has been used successfully to treat patients with a range of malignancies including melanoma, prostate, and renal cancer, and was approved in 2011 by US regulators for the treatment of melanoma." (PMID 25573348, 2015). "At present, there are three classes of therapies approved for melanoma, the alkylating agents such as dacarbazine, the targeted therapies such as the selective inhibitor of BRAF V600E, and immunotherapeutic agents including anti-CTLA-4 antibody and more recently anti-PD-1 antibody." (PMID 25872534, 2015). "Combinational immunotherapy using antibodies to CTLA-4, PD-1/PD-L1, with small molecule inhibitors of indolamine deoxygenase (IDO), have also been shown to lead to improved tumor control and increased IL-2 production by tumor infiltrating lymphocytes (TILs) in an implantable melanoma setting." (PMID 25992292, 2015). "To determine whether sCTLA4 levels correlate with survival in general, rather than only in those patients who are treated with anti-CTLA4, we also tested stage IV melanoma patients who had not received ipilimumab (n = 11)." (PMID 24904825, 2014). "CTLA4 is also expressed on tumor cell lines and in human melanoma; blockade of CTLA4 in vitro induces apoptosis of melanoma cells, indicating that CTLA4 might have non-immune functions." (PMID 24743024, 2014). "The first successful immunotherapy aiming to block a negative regulatory pathway on T cells is the anti-CTLA-4 (Cytotoxic T-Lymphocyte Antigen-4) mAb ipilimumab, which was approved by the FDA (Food and Drug Administration) in 2011 for treatment of patients with advanced melanoma." (PMID 24829760, 2014). "Because it was known that there are no characteristic simple CTLA-4 genotype patterns that would differentiate healthy controls from melanoma cases, we instead looked for differences in distances from the all possible RRP1−RRP20 pairs that would maximize the separation of the two sub-cohorts." (PMID 24475110, 2014). "Also CTLA-4 transcripts were found expressed in melanoma tissue sections consisting of melanoma cells without detectable tumor infiltrating lymphocytes." (PMID 23634660, 2013). "Nevertheless, whether human anti-CTLA-4 antibodies could induce ADCC of CTLA-4+ melanoma cell targets has not yet been investigated." (PMID 23634660, 2013). "On the other hand, we found that all the melanoma cell lines, but not FO-1, expressed CTLA-4." (PMID 23634660, 2013).